LGALS4 (galectin 4)
Diseases named in the same sentence as LGALS4 in open-access papers (continued):
Sharing a sentence is not in itself a finding about the gene and the disease.
pancreatic ductal adenocarcinoma (3 papers, 2014 to 2019). An infiltrating adenocarcinoma that arises from the epithelial cells of the pancreas. "Galectin-4 (Gal-4) has been recently identified as a pivotal factor in the migratory capabilities of a set of defined pancreatic ductal adenocarcinoma (PDAC) cell lines using zebrafish as a model system." (PMID 24977327, 2014).
colorectal tumors (2 papers, 2020 to 2024). "LGALS4 was also found elevated in the serum and colorectal tumors and associated with poor prognosis." (PMID 38612533, 2024).
multiple sclerosis (2 papers, 2022 to 2023). A progressive autoimmune disorder affecting the central nervous system resulting in demyelination. "In particular, Gal-1 was found in neurofilamentous lesions of patients affected by amyotrophic lateral sclerosis (ALS), while patients with multiple sclerosis showed a higher concentration of Galectin 4 (Gal-4) in chronic lesions of the brain." (PMID 37298672, 2023).
psoriasis (2 papers, 2017 to 2025). An autoimmune condition characterized by red, well-delineated plaques with silvery scales that are usually on the extensor surfaces and scalp. "Additionally, a higher plasma level of galectin-4 is associated with an increased likelihood of forming carotid plaque, which is commonly observed in patients with psoriasis." (PMID 41226378, 2025). "In our research, galectin 4 was significantly positively related to both BMI and psoriasis duration." (PMID 41226378, 2025). "However, galectin-4 was significantly positively related to BMI and psoriasis duration (R = 0.27, p = 0.03; R = 0.28, p = 0.03, respectively)." (PMID 41226378, 2025). "In this study, we evaluated plasma levels of galectin-4 and galectin-10 in patients with psoriasis." (PMID 41226378, 2025). "It has been shown that galectin-4 directly stimulates CD4+ T cells to produce IL-6, which contributes to the development of IBD, a condition closely related to psoriasis." (PMID 41226378, 2025). "To the best of our knowledge, we are the first to demonstrate significantly higher plasma concentrations of Charcot–Leyden crystal protein and galectin-4 in patients with psoriasis compared to individuals without the dermatosis." (PMID 41226378, 2025). "Galectin-4 did not correlate with psoriasis severity evaluated with PASI score nor age (R = −0.03, p = 0.80; R = 0.46, p = 2.10, respectively)." (PMID 41226378, 2025).
ulcerative colitis (2 papers, 2023 to 2025). An inflammatory bowel disease involving the mucosal surface of the large intestine and rectum. "Galectin-4 differs from other galectins in carbohydrate-binding specificity, cellular and pathophysiological function, and roles in e.g. cancer progression, fibrosis, and ulcerative colitis, making potent, selective inhibitors desired." (PMID 40735388, 2025).
urothelial carcinoma (2 papers, 2017 to 2020). A malignant neoplasm derived from the transitional epithelium of the urinary tract (urinary bladder, ureter, urethra, or renal pelvis). "LGALS4 could predict a good prognosis of urothelial carcinoma of the bladder and restrained the growth and migration of urothelial carcinoma of the bladder cells." (PMID 33604353, 2020). "Thus, we analyzed LGALS4 methylation and gene expression and their clinical relevance and biological function in urothelial carcinoma (UC)." (PMID 28423602, 2017).
urothelial carcinoma of bladder (2 papers, 2020 to 2023). "It is reported that LGALS4, a β-galactoside binding protein, is correlated with prognosis in urothelial carcinoma of bladder and is also a tumor marker in serum immunoassay determination of colorectal carcinoma." (PMID 36759514, 2023).
adenocarcinoma in situ (1 paper, 2013). A lesion in which the normally situated glands are partially or completely replaced by atypical cells with malignant characteristics. "On the other hand, only 1 adenocarcinoma in situ (1.5%) and 1 minimally invasive adenocarcinomas (2.2%) expressed galectin-4." (PMID 24339976, 2013).
aortic valve stenosis (1 paper, 2021). Aortic valve stenosis (AVS) is a condition characterized by narrowing of the heart's aortic valve opening. "Associations were found between the development of aortic valve stenosis in patients with coronary atherosclerosis and certain proteins, such as differential growth factor-15, galectin-4, the Willebrand factor, interleukin 17, transferrin receptor protein 1 and PCSK9." (PMID 34948066, 2021).
Barrett esophagus (1 paper, 2019). Esophageal lesion lined with columnar metaplastic epithelium which is flat or villiform. "Expression of LGALS4 and TFAP2B show higher or lower expression in Barrett's esophagus, respectively, and this level of expression is maintained in EAC, mirroring the loci accessibility patterns." (PMID 30962179, 2019). "Genome Browser tracks of the LGALS4 (gained accessible region) and TFAP2B (lost accessible region) loci illustrate the “maintenance” of chromatin accessibility states in EAC compared to Barrett's esophagus." (PMID 30962179, 2019).
carcinoid tumor (1 paper, 2016). A slow growing neuroendocrine tumor, composed of uniform, round, or polygonal cells having monotonous, centrally located nuclei and small nucleoli, infrequent mitoses, and no necrosis. "In addition, decreased expression of galectin-4 was observed in metastatic ileal carcinoids compared with primary carcinoid tumors in the ileum, indicating that galectin-4 may act as a tumor suppressor in ileal carcinoids." (PMID 27017379, 2016).
colorectal adenoma (1 paper, 2025). An adenoma that arises from the colon or rectum. "At both the mRNA and protein level, LGALS4 is significantly downregulated in colorectal adenomas and was nearly undetectable in invasive carcinomas." (PMID 39948151, 2025).
ductal carcinoma in situ (1 paper, 2010). "The highest levels of galectin-4 expression were found in the ductal carcinoma in situ cases and in a subset of infiltrating ductal carcinomas." (PMID 23658855, 2010).
endometrioid ovarian cancer (1 paper, 2021). "For patients with endometrioid ovarian cancer, LGALS4 showed a favorable OS." (PMID 33854625, 2021).
gallbladder cancer (1 paper, 2026). "In addition, our cohort study showed that high CXCL9 and low LGALS4 in the liver invasion margin demonstrated a favorable prognosis and better responses to anti-PD-1 immunotherapy for patients with gallbladder cancer." (PMID 41766656, 2026).
inverted papilloma (1 paper, 2014). An endophytic benign papillary epithelial neoplasm that results from the invagination and proliferation of epithelial cells in the underlying stroma. "Indeed, epithelial overexpression of galectin-3 (P=0.0002), galectin-4 (P<10−6), galectin-7 (P<10−6) and galectin-9 (P<10−6) was observed in inverted papillomas compared to non-malignant diseases." (PMID 24859692, 2014).
left ventricular hypertrophy (1 paper, 2025). Enlargement of the LEFT VENTRICLE of the heart. "Additionally, increased plasma concentrations of suppression of tumorigenicity-2 (ST2), growth differentiation factor 15 (GDF-15), galectin-4 (Gal-4), and NT-proBNP were associated with incident HF but not consistently with left ventricular hypertrophy or diastolic dysfunction." (PMID 40141349, 2025).
ovarian mucinous carcinoma (1 paper, 2022). "Only one study examined galectin 4 in differentiation between primary ovarian mucinous carcinoma from gastrointestinal cancers that commonly metastasize to the ovaries." (PMID 36050693, 2022).
ovarian mucinous tumour (1 paper, 2006). "Statistical analysis did not reveal any correlation between LGALS4 expression and clinicopathological parameters (age, grade, stage, outcome) in the ovarian mucinous tumour cohort (data not shown)." (PMID 16508639, 2006).
rheumatoid arthritis (1 paper, 2021). A chronic, systemic autoimmune disorder characterized by inflammation in the synovial membranes and articular surfaces. "Anti-galectin-4 and -8 aAbs were found in SLE and rheumatoid arthritis (RA); anti-galectin-7 aAb in SLE; and anti-galectin-8 and -9 aAbs in SLE and RA." (PMID 35008499, 2021).
Stomach Adenocarcinoma (1 paper, 2020). "Intersecting prognostic genes with those with high or medium protein staining in at least 50% of the samples, for example, identifies a noticeable gene for HNSC (COL19A1) and one for Stomach Adenocarcinoma (STAD, LGALS4)." (PMID 33266472, 2020).
tumor (138 papers, 2005 to 2026). "Several studies demonstrated that LGALS4 which encodes galectin-4 acts as a tumor suppressor to reduce the invasion and metastasis of cancer cells and low expression of LGALS4 was significantly associated with shorter disease-free survival." (PMID 36589748, 2022). "Galectin-4 expression was found to be associated with tumor size (p<0.0001), pleural invasion (p = 0.0071), venous invasion (p = 0.0178), nodal status (p = 0.0007), and TNM stage (p<0.0001)." (PMID 24339976, 2013). "Our evaluation of immunohistochemical galectin-4 expression clearly showed that galectin-4 expression is associated with clinicopathologic variables of disease progression such as tumor size, pleural or venous invasion, nodal status, and TNM stage." (PMID 24339976, 2013). "LGALS4’s association with malignant cells may reflect its role in tumor-specific pathways, while MTHFD1’s broader expression suggests its involvement in both cancer cell proliferation and microenvironmental interactions." (PMID 39857769, 2025). "We used IF for the basal PDAC phenotype marker, HMGA2, and the classical marker, Galectin-4 (GAL4), to assess tumor phenotypes semiquantitatively." (PMID 41006303, 2025). "The TIDE (tumor immune dysfunction and exclusion) analysis revealed a strong association of MTHFD1 and LGALS4 expression with immunotherapy outcomes in PRAD." (PMID 39857769, 2025). "Galectin‐4 (Lgals4) is secreted from colonic epithelial cells and has likewise been shown to promote intestinal inflammation and tumor progression through stimulation of IL‐6." (PMID 39392222, 2025). "Conversely, downregulation of genes, like LGALS4 and LTF, is linked to tumor progression and metastasis." (PMID 40802546, 2025). "The tumor cell-resident galectin-4 possibly mediates metastasis through interactions with ABH antigen-binding glycoproteins present on the surface of red blood cells." (PMID 36873388, 2023). "Under inflammatory conditions, galectin-4 suppresses tumor growth by stimulating memory CD4+ T cell expansion." (PMID 36873388, 2023). "In sharp contrast with these studies, the galectin-4 function was also proposed to enhance tumor angiogenesis and metastasis." (PMID 36873388, 2023). "For example, while the stroma is enriched in the expression of Galectin-1, Galectin-4 is expressed mainly by tumour cells." (PMID 35017635, 2022). "Galectin-4 is mainly secreted by epithelial tumor cells and less frequently expressed by stromal cells." (PMID 36428567, 2022). "LGALS4 inhibits tumor cell infiltration, and LGALS4 upregulation prolongs disease-free survival in CRC." (PMID 35572595, 2022). "In CRC, expression of galectin-4 was dramatically decreased compared to normal colon tissues and this condition promoted tumour progression and metastasis." (PMID 27017379, 2016). "With the LGALS4 antibody the ITAC tumor cells displayed a strong cytoplasmic and membranous staining with an additional nuclear staining in the well-differentiated adenocarcinomas." (PMID 19903339, 2009). "This trend was confirmed by the P5 case where LGALS4 was overexpressed only in the "colonic-type" component and not in the poorly differentiated "solid-type" component of the tumor." (PMID 19903339, 2009). "We have hereby opened up a new field of investigation into biomarkers of this tumor type and have identified two promising candidate genes: LGALS4 and CLU." (PMID 19903339, 2009). "Moreover, the CC niche was proximal to the tumor core, where tumor cells induced CD8+ T cell exhaustion via LGALS4 expression." (PMID 41766656, 2026). "These interactions could be blocked by a specific LILRB3 mAb, which retarded tumour growth in galectin-4 expressing MC38 tumour bearing preclinical models." (PMID 40385641, 2025). "Given the involvement of galectin-4 in tumor metastasis in the digestive system, the result suggests that inhibitory oligosaccharides based on the T-antigen could selectively block key interactions." (PMID 40037288, 2025).
tumor (continued). "LGALS4 may play a critical role in tumor-specific pathways, while MTHFD1 may be involved in both cancer cell proliferation and microenvironmental interactions." (PMID 39857769, 2025). "Galectin-4 was proposed as a tumor suppressor inhibiting cell proliferation by down-regulating wingless/integrated (Wnt) and IL-6/NF-κB/Signal transducer and activator of transcription 3 (STAT3) signaling that balance epithelial cell homeostasis in the intestine." (PMID 36873388, 2023). "The decrease in LGALS4 expression may activate Wnt/β-catenin signaling pathway in cytoplasm, leading to survival of tumor cells." (PMID 37535601, 2023). "LGALS4 is considered as a tumor suppressor in CRC and mediates cell adhesion." (PMID 37535601, 2023). "Besides galectin-4, which has been described as a tumor suppressor by inhibiting tumor cell migration and invasion, the other galectins favor pancreatic tumor." (PMID 33889150, 2021). "In many cases, the authors observed that expression of galectin-4 was downregulated in patients with advanced stages of the disease and patients with good survival, leading to the hypothesis that galectin-4 may act as a tumor suppressor, at least for specific types of cancer." (PMID 37753083, 2023). "Galectin-4 (LGALS4) is mainly expressed in the luminal epithelia of the gastrointestinal tract and is reported to have tumor suppressive effects." (PMID 39948151, 2025). "In particular, galectin 4 (LGALS4) was highly and specifically expressed in MOC, but expressed at lower levels in benign mucinous cysts and borderline (atypical proliferative) tumours, supporting a malignant progression model of MOC." (PMID 16508639, 2006). "Transcripts encoding 2 other antigens with cancer-related serological profiles, HSPCA and galectin 4, have been reported to be overexpressed in 45% (20 of 45) and 80% (four of five) in HCC patients, respectively; their upregulation in HCC may associate with occurrence and progression of tumour." (PMID 15756260, 2005). "The gene LGALS4 exhibited the highest expression in tumor cells, while the gene VEGFA from the MAPS signature was highly expressed in various cell types, including myeloid cells and tumor cells." (PMID 38555418, 2024). "LGALS4 is expressed at significantly higher levels in adjacent normal tissues than in CC tissues, and it has been suggested to function as a tumor suppressor in CRC." (PMID 36941538, 2023). "Another study established oligonucleotide microarray analysis in different histological OCs, and showed that galectin 4 (LGALS4) was highly and specifically expressed in mucinous EOC but exhibited lower expression in benign mucinous cysts and borderline (atypical proliferative) tumor." (PMID 34631583, 2021).
cancer (70 papers, 2005 to 2025). A tumor composed of atypical neoplastic, often pleomorphic cells that invade other tissues. "Intracellular galectin-4 interacts with β-catenin, leading to the inhibition of the Wnt pathway-associated cell proliferation and cancer growth." (PMID 36873388, 2023). "Galectin-4 promotes cancer cell adhesion to vascular endothelial cells by interaction with the Thomsen-Friedenreich (TF) disaccharide on cancer-associated MUC1." (PMID 27017379, 2016). "Consequently, the galectin-4 deficiency was associated with early cancer recurrence and death, defined as occurring twelve months after curative surgery." (PMID 36873388, 2023). "Additionally, elevated galectin-4 expression has been associated with numerous cancer types, contributing to cancer pathogenesis through a variety of mechanisms ranging from increased metastatic behavior to the downregulation of pro-apoptotic proteins p21 and Bax." (PMID 38927753, 2024). "Previous studies have demonstrated that the expression of galectin-4 varies across different types and stages of cancer." (PMID 39857769, 2025). "In summary, the available evidence supports the notion that LGALS4 is a potential therapeutic target in tumorigenesis and cancer progression." (PMID 39857769, 2025). "LGALS4, a lectin galactoside-binding soluble 4, exhibits specific expression in the colon and plays a role in the invasion of cancer cells." (PMID 38555418, 2024). "The development of an elegant HCT-116 colon cell model where expression of the gene encoding human galectin-4 is regulated by doxycycline will likely contribute significantly to improving our understanding of the role of galectin-4 in cancer progression." (PMID 37753083, 2023). "In conclusion, our results demonstrate that galectin-4 expression affects the glycan profile of GSLs in malignant cancer cells with a high potential for peritoneal dissemination." (PMID 37569679, 2023). "Galectin-4 has been detected in many cancer types; however, it plays contradictory roles in different types of cancer cells." (PMID 37569679, 2023). "Our results demonstrate that galectin-4 is an important regulator of glycosylation in cancer cells and galectin-4 expression affects the glycan profile of GSLs in malignant cancer cells with a high potential for peritoneal dissemination." (PMID 37569679, 2023). "Galectin-4 has been reported in many cancers, and its expression is related to growth and progression." (PMID 37305017, 2022). "In 2017, an interaction between cancer cells and erythrocytes was reported and interpreted by galectin-4 interaction with the blood group antigen." (PMID 37305017, 2022). "ATF5 expression suppression sensitizes cancer cells to anchorage-dependent death signals, while LGALS4 induction recovers cell-cell junctions." (PMID 34249670, 2021). "The overexpression of galectin-4 in PCa cell lines, along with the altered O-glycosylation, promoted cancer metastasis to lungs." (PMID 32075174, 2020). "We next performed immunohistochemical (IHC) analysis to evaluate gal-4 protein expression in 12 samples of UC in relation to the tumor T category because of the potential biological relevance of LGALS4 expression in cancer progression." (PMID 28423602, 2017). "Up to now, although there is a number of published data regarding galectin-4 expression in cancer, the available information is remained limited." (PMID 27017379, 2016). "Galectin-4 plays divergent roles in cancer and inflammatory conditions, either promoting or inhibiting each disease progression, depending on the specific pathological condition." (PMID 26828567, 2016). "Recently, many studies have been performed with the aim to clarify the interaction between galectin-4 and physiological regulation, intestinal inflammation and cancer." (PMID 27017379, 2016). "The role that galectin-4 plays in malignant-tumor progression and metastasis is dependent on the specific type of cancer." (PMID 26828567, 2016).